TLR4 (toll like receptor 4)
Diseases named in the same sentence as TLR4 in open-access papers (continued):
Sharing a sentence is not in itself a finding about the gene and the disease.
gastrointestinal lymphoma (1 paper, 2025). A non-Hodgkin or Hodgkin lymphoma that arises from any part of the digestive system, with the bulk of the disease localized to that site. "Lachnospiraceae abundantly synthesize butyrate via several intricate metabolic routes, interfering with gastrointestinal lymphoma reinforcing the NF-κB pathway via the MyD88-dependent TLR4 signaling." (PMID 39930533, 2025).
glucose metabolism disorder (1 paper, 2025). "By stimulating the IRS-1/PI3K/AKT signaling system, SE-PP controlled glucose metabolism disorder in adipose tissue, while also inhibiting the TLR4/MYD88/NF-κB pathway to reduce inflammation." (PMID 40941124, 2025).
granulocytosis (1 paper, 2021). "Microbiota derived components, such as LPS through TLR4/MyD88 signaling, induced intestinal IL-17 production and increased G-CSF plasma levels leading to granulocytosis." (PMID 33912172, 2021).
hearing (1 paper, 2012). "Carriage of one or more mutant alleles in combined carriership of TLR4+896 and TLR9 -1237 increases the risk for hearing loss in BM patients (p = 0.0006, OR 4.1, 95% CI 1.8–9.4, in MM patients: p = 0.02, OR 4.3 95% CI 1.3–14.2, in PM patients: p = 0.003, OR 6.0, 95% CI 1.7–21.3)." (PMID 22662111, 2012).
hemophagocytic lymphohistiocytosis (1 paper, 2022). "Lyst has been shown to play an immunoregulatory role in the proinflammatory responses of toll-like receptors (TLRs), namely of TLR3 and TLR4, and has been associated with hemophagocytic lymphohistiocytosis following Epstein–Barr infection in a human patient." (PMID 36142395, 2022).
hemorrhagic disease (1 paper, 2020). Spontaneous or near spontaneous bleeding caused by a defect in clotting mechanisms (blood coagulation disorders) or another abnormality causing a structural flaw in the blood vessels (hemostatic disorders). "In conclusion, heme triggers a wide range of damages via TLR4 signaling, which makes TLR4 a potential candidate for future therapeutic approaches in hemolytic/hemorrhagic diseases." (PMID 33374506, 2020).
hepato-renal syndrome (1 paper, 2021). "The involvement of TLR4 in the hepato-renal syndrome has also been observed in experimental models, where increased renal TLR4 expression has been described, mainly in tubular cells, and related to kidney injury." (PMID 33467524, 2021).
Hernia (1 paper, 2022). "The aim of the study was to determine and evaluate the indicators of TLR4 for different methods of pain relief in anesthetic management of hernia repair in children and their effect on pain chronification." (PMID 36059845, 2022). "The aim of the study was to assess the severity of inflammatory response in children by means of TLR4 indicators while using various regional anesthesia techniques in anesthetic management of hernia repair and their effect on the development of chronic pain syndrome." (PMID 36059845, 2022).
hidradenitis suppurativa (1 paper, 2024). A chronic suppurative and cicatricial disease of the apocrine glands occurring chiefly in the axillae in women and in the groin and anal regions in men. "Variants involved the TLR2 and MPO genes in the first family and the MMP2, GJB2, and TLR4 genes, some of which have already been previously reported as possible candidates for hidradenitis suppurativa." (PMID 39595064, 2024).
hip osteoarthritis (1 paper, 2024). "Necrotic bone tissues from GONFH patients contained a significantly increased macrophage M1/M2 ratio, and higher levels of TLR4, MYD88 and NF‐κB p65 than bone tissues from patients with hip osteoarthritis." (PMID 39123292, 2024).
Hypercalcemia (1 paper, 2021). An abnormally increased calcium concentration in the blood. "The expression of 1αOHase, CD14 and TLR4 was also observed in our case, and might represent the putative mechanism of hypercalcemia, thus treatment with high-dose corticoids was probably responsible for calcitriol secretion control." (PMID 35154010, 2021).
hypercortisolism (1 paper, 2025). "In addition, both mutation of TLR4 and treatment with a TLR4 antagonist inhibited the hypercortisolism observed in diabetic mice." (PMID 40496562, 2025).
Hyperkeratosis (1 paper, 2024). Hyperkeratosis is a histopathological term defining a thickened stratum corneum and may be present in many different skin conditions, with many possible overlaps. "Compared with control mice, mice treated with solenopsin analogues for 28 days showed significant decreases in acanthosis and hyperkeratosis, decreases in TLR4 expression and IL-22, and increases in IL-12." (PMID 39766206, 2024).
Hyperoxaluria (1 paper, 2019). Increased excretion of oxalates in the urine. "Western blot results indicated that the TLR4/NF‐κB pathway was involved in EG‐induced hyperoxaluria." (PMID 31489770, 2019). "Furthermore, treatment with miR‐20b‐3p‐enriched exosomes from ADSCs protected EG‐induced hyperoxaluria rats, and cell experiments confirmed that co‐culture with miR‐20b‐3p‐enriched exosomes alleviated oxalate‐induced cell autophagy and the inflammatory response by inhibiting ATG7 and TLR4." (PMID 31489770, 2019).
hypersplenism (1 paper, 2014). Overactive functioning of the spleen, resulting in excessive destruction of blood cells. "On other hand, the splenic expression of TLR4 might be a further cause of PH due to hypersplenism." (PMID 24976841, 2014).
hypovitaminosis D (1 paper, 2023). "Therefore, the present study aimed at examining the relationship between the TSP1/TLR4 inflammatory pathway and serum vitamin D levels among obese and normal weight subjects with different metabolic phenotypes, as a possible mechanism by which hypovitaminosis D may impact metabolic health." (PMID 37964189, 2023).
IgA vasculitis (1 paper, 2020). "TLR4, the receptor for LPS from Escherichia coli, has been reported with increased mRNA expression in peripheral lymphomononuclear cells of patients with IgAN and in children with IgA vasculitis; in addition, TLR4 is correlated with the signs of innate immunity activation and proteinuria." (PMID 32169051, 2020).
immune thrombocytopenia (1 paper, 2013). "As TLR4 is expressed on both macrophages and DC, we questioned whether IVIg or the CD44 antibody KM114 might utilize the TLR4 pathway in its amelioration of immune thrombocytopenia." (PMID 23940791, 2013).
inflammatory breast carcinoma (1 paper, 2025). An advanced, invasive breast adenocarcinoma characterized by the presence of distinct changes in the overlying skin. "Our study provides novel insights into the significance of TLR4 and AGER in inflammatory breast cancer." (PMID 40647480, 2025). "Understanding the roles of TLR4 and AGER could offer new targets for future therapies and improve outcomes for patients with inflammatory breast cancer." (PMID 40647480, 2025). "However, the role of TLR4 and AGER, specifically in inflammatory breast carcinomas, has not been fully elucidated." (PMID 40647480, 2025).
intracranial meningioma (1 paper, 2020). A meningioma that arises within the cranial cavity. "In the canine brain TLR4 expression has so far only been analyzed in tissue surrounding intracranial meningiomas." (PMID 31959173, 2020).
Intussusception (1 paper, 2018). An abnormality of the intestine in which part of the intestine invaginates (telescopes) into another part of the intestine. "In summary, we have shown that TLR4 is highly expressed on the membranes of intestinal epithelial cells in areas of I/R injury during intussusception." (PMID 29487699, 2018). "The TLR4-PbS QDs localized to areas of intestinal damage in a mouse model of I/R injury during intussusception and in human tissue from pediatric intussusception patients." (PMID 29487699, 2018). "We investigated TLR4 expression in intestinal I/R injury during intussusception." (PMID 29487699, 2018). "We investigated whether TLR4-PbS QDs could be used to detect and monitor intestinal I/R during intussusception." (PMID 29487699, 2018). "Collectively, our data indicate that TLR4 may have an important role in activating the inflammatory response during intussusception." (PMID 29487699, 2018). "Additionally, we evaluated whether anti-TLR4 antibody-conjugated lead sulfide quantum dots (TLR4-PbS QDs) could be used to detect and monitor I/R injury during intussusception." (PMID 29487699, 2018). "We investigated the expression of Toll-like receptor 4 (TLR4) in the acute phase of intestinal I/R injury during intussusception and evaluated whether anti-TLR4 antibody-conjugated lead sulfide quantum dots (TLR4-PbS QDs) could be used to detect and monitor the injury." (PMID 29487699, 2018). "Thus, TLR4-PbS QDs could be used to detect early-stage I/R injury during intussusception." (PMID 29487699, 2018).
keratinocyte carcinoma (1 paper, 2024). A skin cancer arising from the keratin-producing cells of the epidermis. "The study’s objective is to test the association between TLR4 SNPs and the risk of developing keratinocyte carcinomas." (PMID 39684439, 2024). "There is limited information on TLR4 SNPs and susceptibility to human keratinocyte carcinomas." (PMID 39684439, 2024).
Limb tremor (1 paper, 2018). "PD patients with the mixed subtype mainly had the clinical manifestations of limb tremor and muscle rigidity, with serum HMGB1 and TLR4 levels of 5.12 ± 1.07 and 2.43 ± 0.87, respectively." (PMID 29670828, 2018).
long-bone fracture (1 paper, 2015). "Firstly, manipulation of TLR4 trafficking by chaperones has been proposed as a possible medical treatment for septic shock, such as gp96 in the case of long-bone fracture." (PMID 26273144, 2015).
lower respiratory tract infection (1 paper, 2008). "The interaction between pneumolysin and TLR4 was found to contribute to a protective immune response to S. pneumoniae, in particular in a model of upper airway colonization and to a lesser extent during experimental lower respiratory tract infection." (PMID 17711480, 2008). "Our laboratory found a more modest protective role for TLR4 during lower respiratory tract infection by S. pneumoniae, as reflected by a reduced survival and a slightly enhanced bacterial outgrowth after intranasal infection of C3H/HeJ mice with a relatively low infectious dose." (PMID 17711480, 2008).
Löfgren's syndrome (1 paper, 2010). "In addition, we studied the expression of pattern-recognition receptors TLR2 and TLR4, and found that AMs from patients, in particular those with Löfgren's syndrome, had a lower expression of TLR2." (PMID 20813038, 2010).
lupus-like syndrome (1 paper, 2013). "Repeated injections of low-dose LPS (ligand of TLR4/CD14) to female MRL/n, BXSB, or NZW mice accelerates the development of lupus-like syndrome, increasing the production of autoantibodies and worsening the renal function impairment." (PMID 24252506, 2013).
lymphatic disease (1 paper, 2025). "Additionally, mitochondria-related immunometabolic pathways are important for immunological regulation of lymphatic disease spread, for which the Toll-like receptor 4 (TLR4) cascade was most significant." (PMID 39820810, 2025).
lymphoedema (1 paper, 2016). "Because TLR4/MD-2 antibody therapy had been applied to treat lymphoedema by targeting lymphatic vessels in mouse models, our study proposed an unrecognized role of sTLR4/MD-2 complex in CRC prevention." (PMID 27409669, 2016).
macrosomia (1 paper, 2020). "Maternal hepatic TLR4 protein expression was positively correlated with P0 macrosomia and hepatic lipid accumulation in the ethanol-fed maternal mouse liver at E15.5." (PMID 32572070, 2020).
maxillary sinus carcinoma (1 paper, 2024). A carcinoma that arises from the maxillary sinus. "Among the TLR4-expressing OSCCs, HSQ89 and UPCISCC090 were excluded from this experiment because HSQ89 cells are from maxillary sinus cancer and UPCISCC090 cells are HPV-positive OSCCs." (PMID 38254832, 2024).
membranoproliferative glomerulonephritis (1 paper, 2014). Inflammation of the glomeruli characterized by deposits at the intraglomerular mesangium, resulting in thickening of the glomerular basement membrane, activation of complement, and impaired kidney function secondary to damaged glomeruli. "Given recent findings that podocyte TLR4 expression was upregulated in membranoproliferative glomerulonephritis and appeared to contribute to glomerular injury by modulating expression of pro-inflammatory chemokines, it is plausible that TLR activation is a mediator of DN." (PMID 24842252, 2014).
Microscopic hematuria (1 paper, 2020). Microscopic hematuria detected by dipstick or microscopic examination of the urine. "For instance, TLR4 expression is up-regulated in the peripheral blood mononuclear cells of patients with IgAN, particularly in association with proteinuria and heavy microscopic hematuria." (PMID 33324395, 2020).
middle ear cholesteatoma (1 paper, 2020). "An enhanced expression of TLR4 was already shown in 2013 by Hirai and colleagues in middle ear tissues obtained from five patients with acquired middle ear cholesteatoma." (PMID 31947538, 2020). "Middle ear cholesteatoma stem cells (ME-CSCs) showed a significantly increased expression of TLR4 accompanied by a significantly enhanced LPS-dependent pro-inflammatory gene expression pattern of TNFα, IL-1α, IL-1ß, IL-6, and IL-8 compared to non-pathogenic control cells." (PMID 31947538, 2020).
morbid obesity (1 paper, 2020). An excess of body weight, normally defined as an individual with a body mass index greater than 35 or a body weight greater than one hundred percent of ideal body weight. "Therefore, in the present project, we had the following objectives: first, we sought to study circulating levels of cytokines and soluble TLR4 in a cohort of biopsy-proven NAFLD women with morbid obesity (MO) in relation to the hepatic expression of TLRs (TLR2, TLR4, and TLR9)." (PMID 32545403, 2020).
motor neuron degeneration (1 paper, 2021). "Our results support a previous study in the wobbler mouse model of motor neuron degeneration, demonstrating that Nestorone downregulates NF-kB, TLR4, and nNOS proinflammatory factors as well as microglial CD11b expression at the mRNA level." (PMID 33405022, 2021).
motor neuron disease (1 paper, 2018). "TLR4/TLR2 signaling pathways may be involved in neurodegenerative disorders including motor neuron disease, cerebral hypoxia-ischemia and blood-spinal cord barrier dysfunction after ischemia/reperfusion injury, and neuropathic pain." (PMID 29803222, 2018).
mucopolysaccharidosis type 3 (1 paper, 2024). A lysosomal disease characterized by progressive neurocognitive decline, severe intellectual deterioration, loss of functional abilities, and premature death. "In mucopolysaccharidosis type III (MPS III, also known as Sanfilippo syndrome), a pediatric neurodegenerative disorder, accumulation of abnormal glycosaminoglycans (GAGs) induces severe neuroinflammation by triggering the microglial pro-inflammatory cytokines production via a TLR4-dependent pathway." (PMID 39497064, 2024).
mucormycosis (1 paper, 2015). "Compared to hematological controls, individuals with IA and mucormycosis had defective expression of dectin-1; in addition, patients with mucormycosis had decreased TLR2 and increased TLR4 expression." (PMID 25835547, 2015).
muscle atrophy (1 paper, 2024). The loss of muscle tissue due to inactivity or disease. "Muscle atrophy in mice has been associated with microbial antigens, such as the Gram-negative bacterial lipopolysaccharides (LPS), recognized by Toll-like receptor 4 (TLR4) on immune cells, and with gut microbial composition alterations." (PMID 38727321, 2024).
muscular dystrophy (1 paper, 2023). Muscular dystrophy (MD) refers to a group of more than 30 genetic diseases characterized by progressive weakness and degeneration of the skeletal muscles that control movement. "The expression level of eHSP70 and its interaction with TLR4 also controlled the regeneration of skeletal muscles in an animal model of muscular dystrophy." (PMID 37511459, 2023).
Mycobacterium avium infection (1 paper, 2021). "Induce Pro-inflammatory responses dependent on TLR 2, TLR4, and MyD88 in Mycobacterium avium infection." (PMID 35058912, 2021).
myopia (1 paper, 2022). "In mice FDM retina the Tlr4 was decreased, this may fail to down-regulate GABA and led to myopia." (PMID 36418970, 2022).
neisseria gonorrhoeae infection (1 paper, 2023). "Research has shown that activation of Nrf2 and inhibition of NF-κB resulted in a decrease in TLR2/TLR4, which could retard apoptosis and inflammation induced by neisseria gonorrhoeae infection in human endometrial epithelial cells." (PMID 37446399, 2023).
nicotine dependence (1 paper, 2021). Physical and psychological dependence on nicotine. "TLR4 mRNA levels in PBMCs positively correlated with the number of cigarettes smoked per day, smoking index, smoking duration, the number of cigarettes smoked per day, and level of nicotine dependence (all p values < 0.0001)." (PMID 33995400, 2021). "TLR4 mRNA expression levels in PBMCs were positively correlated with the number of cigarettes smoked per day, smoking index, smoking duration, and level of nicotine dependence." (PMID 33995400, 2021).
Niemann-Pick disease, type C1 (1 paper, 2012). Type C Niemann-Pick disease associated with a mutation in the gene NPC1, encoding Niemann-Pick C1 protein. "Three known genes, TLR4 interactor with leucine rich repeats (TRIL), Niemann-Pick disease, type C1, gene-like 1 (NPC1L1), and C4orf7 also termed follicular dendritic cell secreted protein were selected by three of the four methods." (PMID 22606341, 2012).
ocular infection (1 paper, 2018). "Microarray analysis and qPCR did not detect significant changes in ICAM1, CYR61, or PTX3 transcript levels in TLR4−/− following infection, suggesting the importance of TLR4 in eliciting a neutrophil response and complement activation following B. cereus ocular infection." (PMID 29661181, 2018). "Both CCL2 and CCL3 were upregulated in the context of TLR4-mediated inflammation after B. cereus ocular infection, and their blockade might reduce neutrophil infiltration into the vitreous and decrease damage to the retina." (PMID 29661181, 2018).
opisthorchiasis (1 paper, 2025). Infection with flukes of the genus Opisthorchis. "Furthermore, our previous assessment of the liver transcriptome demonstrated the activation of Toll-like Receptor 4 (TLR4) signaling pathways in opisthorchiasis." (PMID 40732668, 2025).
oral candidiasis (1 paper, 2022). Infection of the mucosal lining of the mouth with the fungus Candida albicans. "Of note is that TLR4 has been shown previously to be critical for antifungal defense in an in vitro model of oral candidiasis based on the buccal epithelial carcinoma cell line TR146 and polymorphonuclear leukocytes (PMNs)." (PMID 35208698, 2022).
oral lichen planus (1 paper, 2023). Oral lichen planus is a chronic inflammatory oral condition of unknown aetiology characterized by T-cell-mediated chronic immune response and abnormal epithelial keratinization cycle. "Another soluble TLR-4 isoform was detected in oral lichen planus (OLP) patients, which was shown to produce similar effects of negative regulation since cytokine production was inhibited in activated macrophages." (PMID 37630236, 2023).
oropharyngeal squamous cell carcinoma (1 paper, 2023). "In HPV-associated oropharyngeal squamous cell carcinoma (OPSCC), TLR4 protein expression was lower while higher levels of TLR9 mRNA were observed." (PMID 37180114, 2023).
pancolitis (1 paper, 2025). Ulcerative colitis that involves the entire colon. "A mutant variant of TLR4 affecting exon 3 of TLR4, resulting in a change in the amino acid Asp299Gly, has been observed to be present in 14% of patients with UC and has clinical significance in the UC phenotype, involved with specific clinical features such as pancolitis." (PMID 39936954, 2025).